URGCP (upregulator of cell proliferation)
Diseases named in the same sentence as URGCP in open-access papers (continued):
Sharing a sentence is not in itself a finding about the gene and the disease.
squamous cell carcinoma (1 paper, 2015). A carcinoma arising from squamous epithelial cells. "A high level of URGCP expression was also associated with a poor prognosis in NSCLC patients stratified into distinct histology subtypes, including squamous cell carcinoma, adenocarcinoma and others." (PMID 26429875, 2015).
virus infection (1 paper, 2020). "URGCP (upregulator of cell proliferation, also known as URG4) is previously shown to be upregulated following virus infection, resulting in cell growth/proliferation, and the gene may play a role in proliferation of the gill epithelium also in SGPV-infected salmon." (PMID 33013908, 2020).
cancer (9 papers, 2012 to 2023). A tumor composed of atypical neoplastic, often pleomorphic cells that invade other tissues. "Upregulator of cell proliferation 4 (URG4) has been implicated in the oncogenesis of certain cancers." (PMID 25427922, 2014). "However, we demonstrated that silencing URGCP in NSCLC cells shows a remarkable therapeutic effect in vivo, resulting in almost complete suppression of distant metastasis, suggesting that URGCP might represent a potential therapeutic target for anti-cancer strategies in NSCLC." (PMID 26429875, 2015). "As shown in our, URGCP/URG4 protein expression was predominantly detected in the cytoplasm of tumor cells, and the expression of URGCP/URG4 was significantly higher in cancer lesions than in the adjacent non-cancerous tissues (P<0.001)." (PMID 22815774, 2012).
tumor (9 papers, 2012 to 2023). "To further assess the effect of URGCP/URG4 on resistance to cisplatin-induced apoptosis, we determined its function in vivo by inoculating nude mice with tumor cells." (PMID 26429874, 2015). "Based on these findings, URG4/URGCP has been suggested to function as an oncogene in multiple tumor types." (PMID 25947641, 2015). "We examined the effect of URGCP/URG4 on chemotherapeutics-induced cell apoptosis, by exposing these cells to anti-tumor agent cisplatin." (PMID 26429874, 2015). "Quantitative analysis of the IHC staining indicated that URGCP expression gradually increased in NSCLC tumor tissues at stages I and II and became markedly higher at stages III and IV." (PMID 26429875, 2015). "Consistently, in vivo s.c. xenograft model showed increase in tumor growth of URGCP-overexpressing NSCLC cells as compared with that of vector-control cells." (PMID 26429875, 2015). "The present study demonstrate that up-regulator of cell proliferation (URGCP), a recently identified tumor-promoting gene found in several tumor types, is markedly overexpressed in human NSCLC cell lines and clinical NSCLC samples." (PMID 26429875, 2015). "URGCP/URG4 expression in tumor tissues was determined as strong (score >6) in 122 cases (43.9%) and weakly positive (score 0 to 6) in 156 cases (56.1%)." (PMID 22815774, 2012). "Upregulation of URGCP could promote cell proliferation, whereas downregulation of URGCP could inhibit proliferation and tumor formation of GC cells." (PMID 33854599, 2021). "Nevertheless, the oncogenic roles and the molecular mechanism of URGCP in NSCLC tumor progression remain largely unknown." (PMID 26429875, 2015). "Specifically, the mean tumor volume at the end of the experiment was 589.06±39.1 mm3 for control QGY-7703 cells, versus 188.43±43.0 mm3 for QGY-7703/URGCP-silenced cells, and the corresponding mean tumor weight was of 466.43±47.2 mg and 195.57±34.1 mg, respectively (P<0.05)." (PMID 22815774, 2012). "This study provides the first demonstration that URGCP is a positive regulator of tumor invasion and metastasis in NSCLC, complementing its biological role in promoting cell proliferation, from which URGCP is named." (PMID 26429875, 2015). "Our analysis revealed the expression of URGCP/URG4 was significantly correlated with degree of differentiation (p < 0.001), larger tumor size (p < 0.001), lymph node involvement (p < 0.001), short survival time (p < 0.001) and vital status(p < 0.001)." (PMID 26429874, 2015). "Up-regulated gene-4 (URG4), also known as upregulator of cell proliferation (URGCP), is overexpressed in multiple tumor types and has been suggested to act as an oncogene." (PMID 25947641, 2015). "In our test cohort, patients with high levels of URGCP/URG4 expression, including those at early stages of HCC (TNM stage I-II, tumor size <3 cm), display a relatively low OS, even as compared with patients with later stages of disease." (PMID 22815774, 2012). "IHC results revealed an upregulation of URGCP/URG4 in all HCC cell lines and fresh HCC samples as compared with normal liver cells and para-tumor tissues, respectively." (PMID 22815774, 2012). "It is of particular note that for QGY-7703 HCC cells with URGCP/URG4 silenced, xenografts exhibited a significantly decreased rate of growth, as evidenced by lower tumor volume and weight." (PMID 22815774, 2012). "Our analysis revealed the expression of URGCP/URG4 was significantly correlated with degree of differentiation (p < 0.001), larger tumor size (p < 0.001), lymph node involvement (N classification) (p < 0.001), short survival time (p < 0.001) and vital status (p < 0.001)." (PMID 26429874, 2015). "URGCP/URG4 is overexpressed in various tumors and plays critical role during tumor development." (PMID 26429874, 2015).
tumor (continued). "IHC analysis revealed URGCP/URG4 was high expression in 106 (61.6%) cases, and low expression in 66 (38.4%) cases, and its expression advanced with larger tumor size (T classification), the detailed date were shown as follow: 37.8% for T1 (34/90), 87.8% for T2 (72/82)." (PMID 26429874, 2015). "Although several studies have indicated that URG4/URGCP may act as an oncogene in various tumor types, the exact function and molecular mechanism of actions of URG4/URGCP have not been precisely characterized." (PMID 25947641, 2015). "However, the effect of URG4/URGCP on tumor angiogenesis in HCC has not yet been elucidated." (PMID 25947641, 2015). "In parallel, URGCP protein and mRNA expression was differentially upregulated in all 8 NSCLC tumor samples (T) compared to matched adjacent non-tumor tissues (ANT), with each pair derived from the same patient." (PMID 26429875, 2015). "In the group of patients whose tumor sizes were ≤3 cm in diameter, the 5-year survival rate was 73.7% in the low-URGCP/URG4 group, as opposed to 49.1% for patients exhibiting high URGCP/URG4 expression (P<0.005)." (PMID 22815774, 2012). "URGCP/URG4 expression was analyzed in 15 HCC cell lines, in 278 archived paraffin-embedded HCC sections, and in 10 pairs of fresh HCC tumor and para-tumor non-cancerous tissues using immunohistochemistry (IHC) and Western blotting analysis (WB)." (PMID 22815774, 2012). "However, no evident correlations were observed between URGCP/URG4 expression and age, gender, tumor number recurrence." (PMID 26429874, 2015).
URGCP also shares sentences with these, for which no sentence is quoted: non-small cell lung carcinoma (4 papers); cervical cancer (3); epithelial ovarian cancer (2); nasopharyngeal carcinoma (2); ovarian cancer (2); prostate carcinoma (2); thyroid cancer (2); acute lymphoblastic leukemia (1); adenocarcinoma (1); breast ductal carcinomas (1); cervical tumour (1); colon adenocarcinoma (1); colorectal adenocarcinoma (1); colorectal cancer (1); glioblastoma (1); leukaemia (1); lymph node metastasis (1); medullary thyroid cancer (1).